KCND2 (potassium voltage-gated channel subfamily D member 2)
Diseases named in the same sentence as KCND2 in open-access papers:
KCND2 is named in the same sentence as 73 diseases in open-access papers, as found by Europe PMC text mining. Sharing a sentence is not in itself a finding about the gene and the disease. The quoted sentences say what the papers report.
epilepsy (23 papers, 2013 to 2024). A brain disorder characterized by episodes of abnormally increased neuronal discharge resulting in transient episodes of sensory or motor neurological dysfunction, or psychic dysfunction. "As opposed to KCNQ1, which is predominantly expressed in the adrenal glands and the thyroid, KCND2 is most expressed in brain tissue; KCND2 genetic variants have been associated with both epilepsy and autism." (PMID 30458022, 2018). "Furthermore, reductions in Kv4.2 channel expression and a mutation in the gene encoding Kv4.2 (KCND2) are reported in animal models of epilepsy and patients with temporal lobe epilepsy." (PMID 28993724, 2017). "For example, the transcription of potassium voltage-gated channel subfamily D member 2 encoding A-type potassium channel subunit Kv4.2 is downregulated after TBI, which is associated with hyperexcitability in the post-traumatic rat hippocampus and contributes to subsequent epilepsy." (PMID 33597846, 2020). "Using qRT–PCR, we validated the downregulation of ASD-related genes involved in cerebellar development (Cadps2 and Reln) (refs 28, 43), and ASD- or epilepsy-related ion channels in neurons (Cacna2d1, Grik2 and Kcnd2) (refs 43, 44, 45) in ICRF-193 treated or Chd7 mutant CGNs." (PMID 28317875, 2017). "Recent studies indicated the potential of miRNAs including miR223 as potential therapeutic targets for various diseases, such as K+-channel-related cardiovascular disorders (voltage-gated K+ channel, KV4.2/KCND2) and epilepsy (voltage-gated K+ channels, KV2.1/KCNMB1 and KV7.2/KCNQ2)." (PMID 38892210, 2024).
Arrhythmia (8 papers, 2011 to 2024). Any cardiac rhythm other than the normal sinus rhythm. "Male, but not female, CIH rats have altered expression of Cav3, Cacna1c, Cacnb2, Kcne5, Kcnd2, and Hcn2 which may preferentially predispose postnatal males to develop arrhythmia." (PMID 38981849, 2024). "Except for KCND2, all other genes displayed a very high variability in expression levels in the heart; individuals with high expression levels of those genes could have increased susceptibility to cardiac arrhythmia." (PMID 34743696, 2021). "As we mentioned in previous parts, miR-223-3p induced arrhythmia following myocardial infarction through decreasing KCND2 and Ito, indicating the potential of miR-223-3p to regulate electrophysiological functions of myocardium." (PMID 33553260, 2020).
autism (7 papers, 2015 to 2024). Persistent deficits in social interaction and communication and interaction as well as a markedly restricted repertoire of activity and interest as well as repetitive patterns of behavior. "Impaired closed-state inactivation of Kv4.2 channels caused by a de novo mutation in the KCND2 gene was recently discovered in identical twins affected by autism and intractable epilepsy." (PMID 30009837, 2018). "Recently, exome sequencing of two identical twins affected by autism, with frequent and uncontrollable seizures, revealed a de novo heterozygous variant in KCND2 gene that resulted in the substitution V404M." (PMID 25784856, 2015). "This means that KCND2 is located on the most significant susceptibility locus in autism." (PMID 36756634, 2022).
status epilepticus (6 papers, 2018 to 2023). Status epilepticus is defined as a continuous seizure lasting more than 30 min, or two or more seizures without full recovery of consciousness between any of them. "In mice, kainic acid-induced status epilepticus increases miR-324-5p association with RISC component Ago2 and recruits Kcnd2 mRNA (which encodes Kv4.2) to the RISC." (PMID 30618607, 2018).
atrial fibrillation (4 papers, 2017 to 2024). A disorder characterized by an electrocardiographic finding of a supraventricular arrhythmia characterized by the replacement of consistent P waves by rapid oscillations or fibrillatory waves that vary in size, shape and timing and are accompanied by an irregular ventricular response. "Previous studies have linked dysfunctional Ito arising from mutations to KCND3-encoded Kv4.3 and KCND2-encoded Kv4.2 to atrial fibrillation." (PMID 37122220, 2023). "Gain-of-function variants in KCND2 have been implicated in nocturnal atrial fibrillation." (PMID 34743696, 2021). "This extended gene network contained a number of transcription factors (Tbx5, Hand2, Fhl2, and Gata4) and ion/calcium handling genes (Ank2, Cacna2d2, Scn5a, Kcnd2, Kcnj5, Myoz2, Casq2, Csrp3, and Gja3) of interest in the context of atrial fibrillation." (PMID 28720711, 2017).
breast carcinoma (3 papers, 2017 to 2024). "KCND2 has been identified to be a factor that promotes invasiveness and metastasis potential in breast cancer." (PMID 38728245, 2024). "KCND2 has been earmarked by scientists as a crucial determinant in the prognosis of individuals with breast cancer." (PMID 38728245, 2024). "The protein expression levels of KCND2 in various breast cancer cell lines were examined, which revealed that the expression was elevated in TNBC compared with normal cells or other breast cancer cell types." (PMID 38728245, 2024).
gastric cancer (3 papers, 2023 to 2024). A primary or metastatic malignant neoplasm involving the stomach. "Despite the association of KCND channels, especially KCND2, with the development and progression of various cancers, there remain some limitations in our understanding of the involvement of KCND2 in gastric cancer." (PMID 37347147, 2023). "In similarity with previous publications, our article illustrated that KCND2 in gastric cancer patients had been shown to be highly expressed and linked to poor clinical features and prognosis." (PMID 37347147, 2023). "In conclusion, our article illustrated that KCND2 was upregulated in gastric cancer patients and was implicated in adverse clinical features and clinical prognosis." (PMID 37347147, 2023). "Overall, these findings suggest that KCND2 is likely to be available as an underlying therapeutic target for gastric cancer." (PMID 37347147, 2023). "Therefore, further studies are needed to elucidate the definitive roles of KCND2 in gastric cancer and to explore its potential as a diagnostic or therapeutic target for this disease." (PMID 37347147, 2023). "Moreover, high expression of the potassium voltage-gated channel subfamily D member 2 (KCND2) was associated with poor survival in gastric cancer." (PMID 37654625, 2023). "KCND2, which is a part of the potassium voltage-gated channel subfamily, has been recently reported to promote gastric cancer and lung adenocarcinoma." (PMID 38728245, 2024). "In conclusion, KCND2 contributes to the growth of gastric cancer by activating the NF‐κB through promoting the infiltration of M2 macrophages." (PMID 37347147, 2023). "Univariate and multifactorial analyses demonstrated that KCND2 was an independent predictor of prognosis in gastric cancer." (PMID 37347147, 2023). "KCND2 strengthened the viability at the cellular level by boosting the proliferation of gastric cancer cells and reducing their death rate." (PMID 37347147, 2023). "KCND2 was markedly elevated in gastric cancer and its expression appeared to link to different grades, T stages, and N stages." (PMID 37347147, 2023). "Mechanistically, KCND2 was found to lead to the infiltration of M2 macrophages through activation of NF‐κB, ultimately promoting the advancement of gastric cancer." (PMID 37347147, 2023). "The mRNA levels of KCND2 were significantly enhanced in s all gastric cancer cell lines compared to GES‐1 cells, with the highest expression levels in AGS cell lines." (PMID 37347147, 2023). "Aiming to understand better the contribution of KCND2 in promoting gastric cancer cell proliferation through NF‐κB activation, we knocked down KCND2 expression and treated cells with lipopolysaccharide (LPS), a commonly used activator of the NF‐κB pathway." (PMID 37347147, 2023). "We next examined in all the tumors for levels of KCND2, and it was observed that KCND2 was found to be high in a variety of tumors, including gastric cancer from TCGA database." (PMID 37347147, 2023). "Subsequently, the impact of KCND2 on the clinicopathologic characteristics and survival time of patients with gastric cancer was explored." (PMID 37347147, 2023). "Given its importance, we sought to determine whether KCND2 facilitates the development of gastric cancer via activating the NF‐κB pathway." (PMID 37347147, 2023). "In addition, KCND2 was an independent predictor of prognosis, and its elevated levels in TCGA database revealed a more unfavorable prognosis for patients with gastric cancer." (PMID 37347147, 2023). "Additionally, it also highlights that KCND2 the abilities of proliferating of gastric cancer cells by stimulating NF‐κB both in cell and animal levels." (PMID 37347147, 2023). "Therefore, we next overexpressed KCND2 in gastric cancer cells to verify the visualization of nuclear translocations of NF‐κB p65, which is a hallmark of NF‐κB activation." (PMID 37347147, 2023).
gastric cancer (continued). "Furthermore, knocking down KCND2 in cellular and animal experiments resulted in the ability to inhibit gastric cancer cell viability and growth." (PMID 37347147, 2023). "Importantly, our study revealed that KCND2 was able to initiate the development of gastric cancer cells at both the cellular and animal levels, suggesting that KCND2 is critical for the formation and progression of gastric cancer." (PMID 37347147, 2023). "Finally, by mechanism, KCND2 was shown to lead to the infiltration of M2 macrophages through activation of NF‐κB to promote the advancement of gastric cancer eventually." (PMID 37347147, 2023). "Overall, this research provides promising insights into the involvement of KCND2 in the development of gastric cancer and suggests that targeting KCND2 may serve a potential therapeutic strategy for the treating gastric cancer." (PMID 37347147, 2023). "Although the potassium voltage‐gated channel subfamily D (KCND) channels, particularly KCND2 (also known as Kv4.2), have found evidence of involvement in the occurrence and development of various cancers, there are still some limitations in our understanding of KCND2's roles in gastric cancer." (PMID 37347147, 2023). "Furthermore, studies have focused on the association between KCND2 expression and the clinicopathologic features of gastric cancer patients, but relatively little attention has been paid to the functional consequences of KCND2 dysregulation in gastric cancer cells." (PMID 37347147, 2023). "In this study, KCND2 expression was positively correlated with M2 macrophage from TCGA database, and KCND2 could promote the infiltration of M2 macrophages of gastric cancer in vivo, which may be responsible for facilitating the growth of gastric cancer." (PMID 37347147, 2023). "With a view to further verifying the capabilities of KCND2 on gastric cancer cells, we first examined the levels of KCND2 in GES‐1 cells (human gastric epithelial cells) and SGC‐7901, HGC‐27, AGS and MGC‐803 cells (gastric cancer cells) by qRT‐PCR." (PMID 37347147, 2023). "In addition, KCND2 high expression experienced worse prognosis, which included OS, disease‐specific survival (DSF) and progress free interval (PFI) in the patients with gastric cancer." (PMID 37347147, 2023).
mental disorder (3 papers, 2012 to 2021). A disease that has its basis in the disruption of mental process. "Kv4.2 subunit may contribute to oligodendrocyte dysfunction in SPMS brain because dysregulated KCND2 transcripts are associated with oligodendrocyte dysfunction in mental illnesses." (PMID 34276310, 2021).
autism spectrum disorder (2 papers, 2022). A spectrum of developmental disorders that includes autism, and Asperger syndrome.
Brugada syndrome (2 papers, 2011 to 2025). A genetically heterogeneous condition characterized by complete or incomplete right bundle branch block accompanied by ST elevation in leads V1-V3. "Interestingly, the gain-of-function mutations associated with Brugada syndrome have been identified in KCND3 and KCND2 encoding Kv4.2, which constitutes a Kv channel tetramer, along with Kv4.3 in vivo." (PMID 40334257, 2025).
extrapulmonary tuberculosis (2 papers, 2011 to 2012). A tuberculosis that occurs at body sites other than the lung. "Recent reports elsewhere identified that single nucleotide polymorphisms rs4893980 on gene PDE11A of chromosome number 2, rs10488286 on gene KCND2 of chromosome number 7 and rs2026414 on gene PCDH15 of chromosome number 10 in humans were associated with extrapulmonary tuberculosis." (PMID 22770435, 2012).
ganglioglioma (2 papers, 2014 to 2025). A well differentiated, slow growing neuroepithelial neoplasm composed of neoplastic, mature ganglion cells and neoplastic glial cells. "For example, KCND2 has been linked to the regulation of ERK signaling in ganglioglioma, with recurrent copy number breakpoints within KCND2 associated with MET amplification." (PMID 39140252, 2025).
lung adenocarcinoma (2 papers, 2023 to 2024). A carcinoma that arises from the lung and is characterized by the presence of malignant glandular epithelial cells. "KCND2 appears to be overexpressed in lung adenocarcinoma (AD) and its reduction could prevent the proliferation, invasion and migration of AD cells." (PMID 37347147, 2023).
astrocytoma (1 paper, 2024). "Nonetheless, it is still possible to highlight some few exceptional features that were selected DRG2, KCND2, and C14orf23, which allow for the separation of astrocytoma." (PMID 38812741, 2024).
bladder cancer (1 paper, 2023). "KCND2 is also a pivotal gene implicated in the initiation and pathogenesis of bladder cancer." (PMID 37347147, 2023).
ethanol abuse (1 paper, 2025). "Later, we studied KCND/Kv4, Kcnd1, Kcnd2, and Kcnd3, since Kcnd2 has recently been reported to be involved in ethanol abuse." (PMID 41155561, 2025).
hidradenitis suppurativa (1 paper, 2025). A chronic suppurative and cicatricial disease of the apocrine glands occurring chiefly in the axillae in women and in the groin and anal regions in men. "Potassium channels: Pain perception in hidradenitis suppurativa may be significantly influenced by the dysregulation of potassium channels, including genes such as KCNMA1, KCNQ5, KCNB2, KCND2, KCND3, and KCNAB3, all of which were identified in this study." (PMID 39940809, 2025).
intrahepatic cholangiocarcinoma (1 paper, 2023). A carcinoma that arises from the intrahepatic bile duct epithelium in any site of the intrahepatic biliary tree. "FAM66C drives intrahepatic cholangiocarcinoma progression and glycolysis by sponging miR-23b-3p and thus upregulating KCND2 expression." (PMID 37980632, 2023).
ischemic stroke (1 paper, 2023). A stroke disorder caused by obstruction of blood flow to the brain, due to thrombotic (local blood clot formation) or embolic (due to a blood clot or other material traveling from another site) event. "It is well documented that KCND2 upregulates STAT3 in ischemic stroke; therefore, there is speculation whether KCND2 can regulate STAT3 in response to NF‐κB pathway activation, which we will confirm with more follow‐up studies." (PMID 37347147, 2023).
Ito (1 paper, 2014). "Indeed the molecular basis of Ito is Kcnd2/Kv4.2 that has previously been claimed to be transcriptionally regulated by the miR-1 target Irx5 and to be at least in part responsible for cardiac conduction defects observed in miR-1-2 mutant mice." (PMID 25415383, 2014).
long-QT syndrome (1 paper, 2024). "Mutations in Kcnd2 have been associated with long-QT syndrome and/or sudden cardiac death." (PMID 39304345, 2024).
nicotine addiction (1 paper, 2024). "KCND2 participated in signaling pathways related to endocrine and other factor-regulated calcium reabsorption, nicotine addiction, and synaptic vesicle cycle." (PMID 38846945, 2024).
cancer (6 papers, 2016 to 2025). A tumor composed of atypical neoplastic, often pleomorphic cells that invade other tissues. "In addition, the findings provided proof that in animal levels, KCND2 might regulate the immune system by associating with promoting M2 macrophages, which are known to play critical roles in cancer progression." (PMID 37347147, 2023). "For CNV deletions, only three genes (KCND2, SDK1, SP4) displayed more than three instances across different BD‐cancer patients." (PMID 39140252, 2025). "The potassium voltage‐gated channel subfamily D (KCND, also known as Kv4) consists of three members, including KCND1 (Kv4.1), KCND2 (Kv4.2), and KCND3 (Kv4.3), which have been widely documented to be responsible for the initiation and advancement of cancers." (PMID 37347147, 2023).
tumor (3 papers, 2022 to 2024). "By profiling the TCGA database, we found that KCND2 was involved in tumor‐associated pathways and immune processes through GO and KEGG enrichment." (PMID 37347147, 2023). "Consistent with the results from cellular studies, knockdown of KCND2 prevented tumor growth compared with controls, while activating of the NF‐κB by LPS reversed the shrinkage among tumors due to KCND2 knockdown." (PMID 37347147, 2023). "Additionally, immunofluorescence, flow cytometry and quantitative real‐time polymerase chain reaction (qRT‐PCR) techniques were used to investigate tumor proliferation and immune cell infiltration at different levels of KCND2 expression in vivo." (PMID 37347147, 2023). "Interestingly, KCND2 was found to be in positive correspondence with stromal cell and immune cell scores, suggesting that KCND2 appeared to be able to regulate the tumor microenvironment (TME)." (PMID 37347147, 2023).
KCND2 also shares sentences with these, for which no sentence is quoted: temporal lobe epilepsy (10 papers); depression (6); heart failure (5); myocardial infarction (5); Ventricular arrhythmia (4); cardiac arrhythmia (3); cardiac diseases (3); cardiac hypertrophy (3); diabetes (3); Alzheimer disease (2); anxiety disorder (2); diabetic cardiomyopathy (2); hypothyroidism (2); schizophrenia (2); Seizure (2); Anxiety (1); aortic coarctation (1); bipolar disorder (1); Blindness (1); brain malformations (1); cardiovascular disorder (1); cerebellar ataxia (1); Chorea (1); cognitive deficits (1); colitis (1); developmental delay (1); diabetic neuropathy (1); Dystonia (1); encephalitis (1); Focal cortical dysplasia (1).
A further 19 diseases each share a sentence with KCND2 in 1 paper.